NUDC (nuclear distribution C, dynein complex regulator)
Description:
Plays a role in neurogenesis and neuronal migration (By similarity). Necessary for correct formation of mitotic spindles and chromosome separation during mitosis. Necessary for cytokinesis and cell proliferation.
Synonyms: HNUDC; MNUDC; NPD011
Tractability: PROTAC: ubiquitination databases record sites on it; its protein half-life has been measured.
Gene: Protein-coding gene on chromosome 1 (26,900,238 to 26,946,885, forward strand). Ensembl gene ENSG00000090273.
Subcellular location: Cytoplasm, cytoskeleton; Nucleus; Cytoplasm, cytoskeleton, spindle; Midbody
Subcellular location (Human Protein Atlas): Cytosol
Pathways (Reactome):
Cell Cycle: Amplification of signal from unattached kinetochores via a MAD2 inhibitory signal; EML4 and NUDC in mitotic spindle formation; Mitotic Prometaphase; Resolution of Sister Chromatid Cohesion; Separation of Sister Chromatids
Signal Transduction: RHO GTPases Activate Formins; RND2 GTPase cycle
Gene Ontology:
Molecular function: cadherin binding; protein binding
Biological process: mitotic metaphase chromosome alignment; mitotic spindle organization; nuclear migration; response to peptide hormone
Cellular component: cytoplasm; midbody; mitotic spindle; nucleus; cytosol; nucleoplasm; spindle; cytoskeleton
Genetic constraint (gnomAD): Loss-of-function variants: 14 observed, 42.87 expected, observed/expected ratio (o/e) 0.33, 90% interval 0.22 to 0.51. The upper end of that interval is the gene's LOEUF score, 0.51, which puts it in group 2 of 6, group 1 being the genes least tolerant of losing a copy. Missense variants: 323 observed, 422.09 expected, observed/expected ratio (o/e) 0.77, 90% interval 0.7 to 0.84. Synonymous variants: 153 observed, 161.27 expected, observed/expected ratio (o/e) 0.95, 90% interval 0.83 to 1.09.
Homologues: Orthologues: chimpanzee NUDC (99% identical), macaque NUDC (99% identical), rabbit NUDC (97% identical), dog NUDC (96% identical), pig NUDC (95% identical), rat Nudc (95% identical), mouse Nudc (94% identical), guinea pig NUDC (94% identical), zebrafish nudc (73% identical), tropical clawed frog nudc (70% identical), Drosophila melanogaster nudC (52% identical), Caenorhabditis elegans nud-1 (50% identical). Paralogues in human: NUDCD3 (28% identical), NUDCD2 (11% identical).
Diseases named in the same sentence as NUDC in open-access papers:
NUDC is named in the same sentence as 12 diseases in open-access papers, as found by Europe PMC text mining. Sharing a sentence is not in itself a finding about the gene and the disease. The quoted sentences say what the papers report.
clear cell renal cell carcinoma (1 paper, 2024). "In clear cell renal cell carcinoma, PUS10 inhibits RCC migration through the PUS10/miR-194-5p/NUDC/Cofilin1 pathway, and this effect is independent of its catalytic activity." (PMID 39247811, 2024).
colon cancer (1 paper, 2022). "The mRNA expression of LIS1, a downstream molecule of NUDC / LIS1 / dynein pathway, was also significantly increased in NudCD1 overexpressed colon cancer cells, whereas the S phase was relatively shortened." (PMID 36104662, 2022).
tuberculosis (1 paper, 2011). A chronic, recurrent infection caused by the bacterium Mycobacterium tuberculosis. "tuberculosis clinical isolates from China revealed that nudC from most isolates harboured another mutation (residue 239), and a few isolates even had multiple mutations." (PMID 22026918, 2011).
cancer (2 papers, 2023 to 2024). A tumor composed of atypical neoplastic, often pleomorphic cells that invade other tissues. "According to our microRNA sequencing and online data, we revealed that PUS10 could facilitate the maturation of miR-194-5p and subsequently regulate NUDC/Cofilin1-dependent cytoskeleton dynamics to inhibit RCC cancer migration." (PMID 37596681, 2023).
NUDC also shares sentences with these, for which no sentence is quoted: acute myelogenous leukemia (1 paper); bladder cancer (1); breast carcinoma (1); infection (1); non-small cell lung carcinoma (1); prostate carcinoma (1); renal cell carcinoma (1); tumor (1).